VEGFA (vascular endothelial growth factor A)
Diseases named in the same sentence as VEGFA in open-access papers (continued):
Sharing a sentence is not in itself a finding about the gene and the disease.
tumor (continued). "Furthermore, our analysis of the relationship between BAP31 and tumor-associated antigens revealed a positive correlation between BAP31 expression and the levels of GAL-3 and VEGFA." (PMID 38474195, 2024). "VEGFA exhibited significant overexpression in tumor tissues and PC cell lines." (PMID 39606802, 2024). "Expression analysis showed that MMP3, MMP9, TIMP1 and VEGFA were upregulated in tumor samples." (PMID 39177661, 2024). "Therefore, the complex nature of angiogenesis involves a network of diverse growth factors beyond VEGFA, highlighting the complexity of the processes shaping the tumour microenvironment after anti-angiogenic interventions." (PMID 38397987, 2024). "Furthermore, p38 MAPK favors BC growth and metastatization by acting on the tumor microenvironment and enhancing tumor vascularization through the increase of several pro-angiogenic cytokines, such as vascular endothelial growth factor A and IL6." (PMID 37979099, 2024). "Furthermore, the expression of VEGFA was positively correlated with tumor staging, which are in line with the data from PC patients in our hospital." (PMID 39606802, 2024). "We suggest that the increased appearance of small, category 4 shapes in WT mouse LECs upon tumor challenge was at least in part because of VEGFA up-regulation in the hypoxic tumor environment and signal transduction via VEGFR2 pY949 and c-Src, causing VE-cadherin internalization and degradation." (PMID 38148112, 2024). "In addition to promoting tumor metastasis and angiogenesis by secreting VEGFA, CAFs also secrete TGF-β, IL-6, and CC-chemokine ligand 2 to recruit immunosuppressive cells and suppress antitumor immunity." (PMID 38898505, 2024). "The VEGFR2-inhibiting tyrosine-kinase inhibitor sunitinib and the anti-VEGFA antibody bevacizumab have been shown to reverse tumor endothelial cell anergy and stimulate lymphocyte infiltration in human renal cell cancer treated with these drugs in a neoadjuvant fashion." (PMID 39766150, 2024). "Then, using CCK8, wound healing, transwell, scanning electron microscopy, immunofluorescence, flow cytometry, and other techniques, the alterations in tumor malignancy-connected cell behaviors and microstructures were photographed and evaluated in a VEGFA-gene-deleted GC cell line (VEGFA−/−SGC7901)." (PMID 39457390, 2024). "We hypothesized that the zippering of dermal lymphatic junctions and the shape shift of VE-cadherin fragments in the tumor periphery may be related to production of VEGFA and/or VEGFC, which both bind to VEGFR2, in the tumor microenvironment." (PMID 38148112, 2024). "In addition, vascular endothelial growth factor A (VEGF-A), matrix metalloproteinase 13, and vasorin in tumor-derived EVs are transported to ECs and enhance their angiogenic potential." (PMID 38318528, 2024). "This indicated that apatinib combined with PD-1 inhibitor could inhibit tumor angiogenesis by inhibiting the expression of VEGFA and VEGFR2, and then c-Myc, and the inhibitory effect was even more evident with the combined administration of CPT." (PMID 38532022, 2024). "In addition, VEGFA is considered the primary mediator in tumor angiogenesis induced by hypoxia, and one of the downstream genes of NF-kB, leading to neovascularization and apoptotic resistance in GBM." (PMID 39516471, 2024). "However, VEGFA+MC was produced in large quantities in ccRCC tissues and promoted tumor angiogenesis compared with adjacent normal tissues, which aroused our concern." (PMID 39840068, 2024). "The expression of VEGFA in the xenograft tumor also revealed that sh-ANXA9 and sh-S100A4 could decrease it." (PMID 38609357, 2024). "Additionally, studies have shown that VEGFA/VEGFR2 inhibitors can lead to increased aggressiveness of tumours." (PMID 38256941, 2024). "Moreover, both tumor suppressor genes have other SL partners, including VEGFA and PRMT5, defining a dysfunctional network with multiple vulnerabilities that confer treatment opportunities for network takedown." (PMID 38187871, 2024).
tumor (continued). "VEGFA is a major angiogenic factor critical in tumor angiogenesis." (PMID 39319846, 2024). "On the other hand, the expression of genes TOP1, EGFR, STAT3, NR3C1, VEGFA, and AR was upregulated, which could promote tumor cell growth." (PMID 38297292, 2024). "Although VEGFA was initially identified because of a surgeon’s clinical observation about the close association of blood vessel and tumor growth, antiangiogenesis therapies have not been as effective in cancer treatment as initially hoped." (PMID 39087477, 2024). "VEGFA is highly expressed during tumor angiogenesis and closely related to tumor angiogenesis." (PMID 38630355, 2024). "Moreover, VEGFA has been linked to promoting cancer stem cell self-renewal and EMT while contributing to tumor metastasis in BC cells." (PMID 39411137, 2024). "However, the transcriptional profile changed in the tumor with a significant upregulation of ccRCC signature genes VEGFA, NDUFA4L2, and PDK4 both in the primary and the metastatic setting." (PMID 38281962, 2024). "Moreover, YY1 induces vascular endothelial growth factor A (VEGFA) expression by directly binding to the promoter region of VEGF, thereby upregulating their transcription and promoting neovascularization to supply oxygen and nutrients to tumor cells." (PMID 38893192, 2024). "VEGFA is the main driver of angiogenesis in the tumor microenvironment in several cancers." (PMID 38169627, 2024). "Notably, the proportion of neutrophils increased in the metastatic samples, transcriptionally resembling tumor-associated neutrophils (TAN), with a high expression of VEGFA, LGALS3, OLR1, PROK2, MMP9, and IL1RN." (PMID 38358826, 2024). "To investigate whether UBB’s tumor suppressor function in ccRCC relies on regulating VEGFA, we conducted concurrent overexpression of VEGFA to counteract its suppression caused by increased UBB levels in RCC cells." (PMID 38467852, 2024). "Reciprocally, tumor cell-derived VEGFA contributes to M2 polarization of macrophages in TNBC." (PMID 38169627, 2024). "VEGFA is an important factor of angiogenesis during tumor growth." (PMID 38762695, 2024). "VEGFA induces tumor angiogenesis by regulating the expression of a series of downstream products to achieve enhanced vascular endothelial cell viability and the formation of an abnormal tumor vascular system." (PMID 38306566, 2024). "In addition, macrophages are an essential source of VEGFA within the tumor microenvironment, exerting a pro-angiogenic effect and facilitating tumor metastasis." (PMID 38658988, 2024). "It was reported that VEGFA could accelerate tumor expansion by stimulating angiogenic milieu, and increasing microvascular density and permeability." (PMID 39606802, 2024). "Together, our results suggest that under hypoxic tumor conditions, abundant proangiogenic factors are released, highlighting VEGFA, which generates 2 different angiogenic phenotypes in male and female GBM patients, linked to sex hormone signaling, especially the expression of ESR1." (PMID 38411438, 2024). "Inhibited VEGFA expression significantly suppressed tumor angiogenesis in CRC cells." (PMID 39177661, 2024). "YTHDF2 acted as a tumor promoter by upregulating PD‐L1 and VEGFA expression in HCC." (PMID 38247171, 2024). "Taken together, melatonin has a tumor suppressive role through influencing miR-424-5p/VEGFA axis." (PMID 37178445, 2024). "VEGFA influences the function of stromal and immune cells within the tumor microenvironment and directly modulates the functionality of tumor cells (Goel and Mercurio, 2013; Pérez-Gutiérrez and Ferrara, 2023), particularly in promoting their survival and proliferation." (PMID 38716237, 2024). "Angiogenesis, facilitated by VEGFA, is crucial for tumor growth and metastasis." (PMID 39337657, 2024).
tumor (continued). "It was recently demonstrated that low-dose radiotherapy (LDRT), in combination with anti-PD-L1 and anti-VEGFA (vascular endothelial growth factor A) therapy, ameliorates the anti-tumor response through the activation of CD8+ exhausted-like T cells (CD8+ Tex) in the tumoral core." (PMID 39408564, 2024). "If bevacizumab exerts direct cytotoxic effects on VEGFA-expressing tumor cells, individual variances in VEGFA expression levels might be a key determinant in the variability of therapeutic responses." (PMID 38716237, 2024). "We also document an immunosuppressive function of VEGFA in the tumor microenvironment (TME)." (PMID 38169627, 2024). "Additionally, VEGFA and Sema 3 A released by tumor cells can activate NRP1, which in turn triggers VEGFR1 activation and enhances TAM recruitment in gliomas." (PMID 39068459, 2024). "Additionally, we identify ligand signalling events occurring between tumour, stroma, and immune infiltrate regions, such as immune infiltrate derived GPNMB, which was highly correlated with VEGFA expression within the tumour." (PMID 38890455, 2024). "The activation of genes such as VEGFA and VEGFR1 under hypoxic conditions underscores the potential of HIF1α and VEGF as biomarkers for aggressive cancer phenotypes, indicating tumor aggressiveness and metastatic potential, which is valuable for prognosis and treatment planning." (PMID 39697237, 2024). "The increase in the miR-424-5p levels mediated by melatonin results in the repression of VEGFA expression, which in turn results in the inhibition of several growth factors related to angiogenesis, suggesting a crucial role of melatonin in tumor suppression via miR-424-5p/VEGFA axis." (PMID 38473317, 2024). "Increased VEGFA expression can lead to immunosuppression by inhibiting dendritic cell (DC) maturation, reducing T cell tumor infiltration, and promoting suppressive cell types in the tumor microenvironment." (PMID 38687357, 2024). "In the present study, the expression of VEGFA was also upregulated in the recurrent tumor slides." (PMID 39375945, 2024). "In the research, we found that knockdown of VEGFA could reverse the influence of miR‐378a‐3p inhibitor on the cell viability of PC cells and tumor growth." (PMID 39606802, 2024). "MAM-derived VEGFA promotes the extravasation and seeding of tumor cells." (PMID 39003350, 2024). "Variants in VEGFA can lead to increased angiogenesis and vascular invasion, as polymorphisms such as -2578 C>A are significantly associated with the development and progression of HCC, highlighting their impact on tumor vascularization and invasiveness." (PMID 39247597, 2024). "The HDAC1 may activate the HIF1α/vascular endothelial growth factor A signaling pathway by directly inhibiting the ubiquitination of HIF1α, which can promote tumor angiogenesis." (PMID 39876842, 2024). "However, the function of VEGFA is not limited to influencing angiogenesis and vascular permeability; its autocrine and paracrine actions also play key roles in tumor initiation and progression." (PMID 38228617, 2024). "Meanwhile, tumor cell-derived VEGFA devoted to polarization of macrophages." (PMID 38169627, 2024). "Additionally, CXCL8hiIL1Bhi macrophages communicated with epithelial cells through VEGFA, contributing to tumor vascular function." (PMID 39229264, 2024). "Along with tissue-resident macrophages, TAMs, which primarily express Tie2, promote the increase in vascular permeability and the infiltration of tumor cells via vascular endothelial growth factor A (VEGF-A) signaling and then promote the distant spread of tumor cells." (PMID 38787372, 2024). "Furthermore, the cooperation between FAK and Krüppel-like factor 8 (KLF8) enhances VEGFA expression, contributing to angiogenesis and tumor growth." (PMID 38338842, 2024). "Tumor cells can secrete VEGFA, PGF, TGF-β, and other cytokines under external stimulation." (PMID 36473369, 2023). "It has been reported that HIF-1α can activate VEGFA and promote tumor angiogenesis." (PMID 37239383, 2023).
tumor (continued). "A high expression level of VEGFA mRNA in tumour tissues indicates a poor prognosis." (PMID 36729917, 2023). "Furthermore, it was reported that miR-106a-5p directly targets the 3′-UTR of VEGFA mRNA and decreases VEGFA expression, followed by degrading effects on tumor cell growth and colony formation." (PMID 37627777, 2023). "In agreement with this, parental or lines generated by culturing KD PML tumors expressed higher levels of HIF1a protein and its target, VEGFa that may account for a higher tumor angiogenic activity." (PMID 37518985, 2023). "Moreover, a human tumor xenograft model also showed that IRE1α/XBP1 induced a proangiogenic response in a VEGFA-independent manner." (PMID 37008067, 2023). "The IL-6 may contribute to the hormone release, to tumor growth and proliferation and to the production of angiogenic factors, such as the vascular endothelial growth factor-A (VEGF-A)." (PMID 36658300, 2023). "The critical role of VEGFA in tumor angiogenesis has been widely studied." (PMID 36999964, 2023). "In addition to promoting tumor progression, myeloid cells have also been implicated in GBM resistance to various therapies, including anti-VEGFA therapy." (PMID 36594465, 2023). "In patients with reduced VEGFA expression, other pathways relevant to regulating angiogenesis and tumor growth could be activated, explaining the resistance of these patients to Ramucirumab treatment." (PMID 37893095, 2023). "Therefore, the low level of miR-106a in RCC tissues was correlated with the upregulation of VEGFA, which contributes to angiogenesis and tumor development." (PMID 37627777, 2023). "Interestingly, in both groups, many of the pathways associated with tumor angiogenesis (VEGFA-VEGFR2, Robo4 and VEGF crosstalk, angiogenesis, and neovascularisition) were significantly upregulated." (PMID 36835505, 2023). "Bevacizumab is a vascular endothelial growth factor A (VEGFA) monoclonal antibody that combines with VEGFA, attenuates VEGFA‐dependent tumor blood vessel formation, normalizes tumor blood vessels, prompts tumor cell apoptosis, inhibits tumor angiogenesis, and finally shrinks the tumor." (PMID 37016906, 2023). "Moreover, TAMs support tumor growth by producing proangiogenic factors, including VEGFA, EGF, and TGF-β1." (PMID 38008741, 2023). "CD31 is an endothelial marker, and VEGFA is a key factor that induces tumor angiogenesis." (PMID 36860928, 2023). "EMT and VEGFA also play a critical role in tumor progression." (PMID 37908231, 2023). "Bevacizumab is the first humanized monoclonal antibody against tumor angiogenesis approved by the U.S. Food and Drug Administration, which can bind to VEGFA, reducing the binding of vascular endothelial growth factor to its receptor and thereby inhibiting vascular growth." (PMID 38203230, 2023). "For correlation analysis of SHH, GLI1 and VEGFA immunoreactivity according to the tumor pathological characteristic and patients’ overall survival we divided patients into groups with clinically early/late, histologically benign/malignant and current state dead/alive." (PMID 37964226, 2023). "Notably, there was a positive association between the levels of ARGs and CNV alteration; for example, the expression levels of PRG2, SERPINA5, and THBD were low in tumor tissues, while VEGFA, PF4, and PTK2 were expressed at high levels." (PMID 37938164, 2023). "Moreover, macrophage-derived VEGFA (vascular endothelial growth factor A) plays a crucial role in tumor angiogenesis in PTEN-null GBM, and α-lactose can attenuated tumor growth by inhibiting angiogenesis in this way50." (PMID 37598273, 2023). "Furthermore, we reported that the association of VEGFA/BRAF targeting with anti‐PD‐1 antibody (triple therapy) resulted in a durable response and enabled complete tumor eradication in 50% of the mice, establishing immunological memory." (PMID 37183363, 2023).
tumor (continued). "The results suggest that CNN1 has a crucial role in angiogenesis and maturation, and CNN1 expression is correlated with the stability of the tumor cytoskeleton, which also influences the migration of tumor cells and the formation of distal lesions together with VEGFA." (PMID 37153789, 2023). "In addition, inhibition of janus kinase 2 (JAK2)/STAT3 was found to reduce MDSCs in the tumor ecosystem through the inhibition of VEGFA and casein kinase 2 (CK2) in HNSCC transgenic mouse models." (PMID 37024932, 2023). "Moreover, the MRS1-tumor cells also can communicate with the microenvironment cells via highly expressing VEGFA, a crucial regulator of pathological angiogenesis, and involve in the proliferation and metastasis of tumor cells." (PMID 37543645, 2023). "A higher tumor VEGFA expression may indicate a better response to bevacizumab, and when combined with the expression of either one of the other proteins (particularly with YKL40), VEGFA expression is even more promising." (PMID 37190125, 2023). "During numerous investigations regarding tumor progression, expression levels of pro-angiogenic regulators, such as vascular endothelial growth factor-A (VEGF-A), basic fibroblast growth factor (bFGF), and angiopoietin 1 and 2 (Ang1, Ang2), are usually increased." (PMID 36829966, 2023). "Endogenous regulators of angiogenesis include a wide range and heterogenous group of factors and the major factor is vascular endothelial growth factor A (VEGF-A).VEGF induces vascular permeability, which enhances the spread of tumor cells into the bloodstream and promotes distant metastases." (PMID 37338718, 2023). "Interestingly, the marker genes in the hypoxic subpopulations were previously shown to be associated with tumor progression, such as SLC2A1 and VEGFA in H1 subpopulation." (PMID 37441593, 2023). "A study demonstrated that the Erk1/2/HIF-1α signaling pathway might promote the angiogenesis of tumor cells by activating VEGFA." (PMID 37239383, 2023). "An interesting cause–effect relationship was also hypothesized in the same study, with a focus on pro-metastastic activity of so-called tumor-educated platelets via the enhanced secretion of Vascular-Endothelial Growth Factor-A." (PMID 37568316, 2023). "In the present study, we found that DOKD may exert its role in inhibiting CT26+ tumor angiogenesis by inhibiting the STAT3/HIF-1α/VEGFA pathway." (PMID 37239383, 2023). "Furthermore, VEGFA 26, known to hinder tumor immunotherapy, demonstrated a positive correlation with the expression levels of NUSAP1 in GBM, KICH, KIRC, KIRP, LUAD, PAAD, SARC, and SKCM." (PMID 37781040, 2023). "Vascular endothelial growth factor A (VEGFA) is involved in regulating biological processes, such as angiogenesis and vascular permeability, and is very closely related to the pathogenesis of various tumours, especially vascular‐rich, solid tumours." (PMID 36729917, 2023). "Upon tumor infiltration, myeloid cells participate in reciprocal interactions with ECs to further promote angiogenesis by multiple mechanisms, including via production of VEGFA." (PMID 36594465, 2023). "Combined blockade of ANGPT2 and VEGFA with a bispecific antibody (A2V) showed superior therapeutic efficacy compared with single agents in genetically engineered and transplanted tumor models, including metastatic breast cancer, pancreatic neuroendocrine tumors, and melanoma models." (PMID 38193080, 2023). "Finally, the results of this study highlighted the role played by exosomes in the transport and diffusion into the tumor microenvironment of some of the factors overexpressed in resistant cells, such as VEGFA, VEGFC, Ang2 and P-gp." (PMID 36874116, 2023). "Interestingly, we found a significant decrease in VEGFA expression in tumor cells with low PD-L1 expression after anti-PD-L1 treatment." (PMID 38152616, 2023).